DOT1L (DOT1 like histone lysine methyltransferase)
Diseases named in the same sentence as DOT1L in open-access papers (continued):
Sharing a sentence is not in itself a finding about the gene and the disease.
osteoarthritis (5 papers, 2017 to 2024). A noninflammatory degenerative joint disease occurring chiefly in older persons, characterized by degeneration of the articular cartilage, hypertrophy of bone at the margins and changes in the synovial membrane. "Pharmacological blockade of SIRT1 effectively reduced the severity of osteoarthritis caused by the DOT1L inhibitor, and reversed the hyper-activation of Wnt signalling." (PMID 28627522, 2017). "Nevertheless, such approaches will be necessary to further understand the role of DOT1L in joint disease, and more in particular in post-traumatic or ageing-associated osteoarthritis." (PMID 28627522, 2017). "Loss of DOT1L disrupts the molecular signature of healthy chondrocytes in vitro and causes osteoarthritis in mice." (PMID 28627522, 2017). "DOT1L inhibition enhanced the osteoarthritis-like gene expression changes, for example, augmenting loss of COL2A1 and gain of COL1A1 expression." (PMID 28627522, 2017). "Thus, DOT1L also protects against osteoarthritis by preventing Wnt-associated ectopic chondrocyte hypertrophy in the articular cartilage." (PMID 28627522, 2017). "Inhibition of SIRT1 protects against osteoarthritis triggered by loss of DOT1L activity." (PMID 28627522, 2017). "We then studied whether loss of DOT1L activity in vivo triggers osteoarthritis, by intra-articular injection of EPZ-5676 into the knees of adult mice." (PMID 28627522, 2017). "DOT1L is one of the few genes linked to osteoarthritis by human GWAS." (PMID 28627522, 2017). "Loss of DOT1L disrupts cartilage homeostasis and triggers the development of osteoarthritis." (PMID 28627522, 2017). "The histone methyltransferase DOT1L protects against osteoarthritis, and DOT1L-mediated H3K79 methylation is reduced in human and mouse osteoarthritic joints." (PMID 34727094, 2021). "Collectively, our data unravel a molecular mechanism that protects against osteoarthritis with hypoxia inducing DOT1L transcription in cartilage." (PMID 34727094, 2021). "Intra-articular treatment with a selective hypoxia mimetic in mice after surgical induction of osteoarthritis restored DOT1L function and stalled disease progression." (PMID 34727094, 2021). "Further studies are necessary to delineate the complex Dot1l regulation of chondrocyte–osteoblast/osteocyte homeostasis and its therapeutic potential in human osteoarthritis and osteoporosis." (PMID 32083237, 2020). "In this study, we show that DOT1L safeguards the homeostasis of the articular cartilage and protects against osteoarthritis." (PMID 28627522, 2017). "Our loss of function data in the articular cartilage resulting in osteoarthritis suggest that specific attention should be given to cartilage in patients treated with DOT1L inhibitors." (PMID 28627522, 2017). "We then examined the therapeutic implications of our findings, and explored the therapeutic potential of blocking SIRT1 in preventing osteoarthritis triggered by DOT1L inactivation." (PMID 28627522, 2017). "Microarray results and subsequent qPCR validation confirmed the induction of osteoarthritis-like gene expression changes upon DOT1L blockade." (PMID 28627522, 2017). "In contrast, local treatment with a selective hypoxia mimetic in the joint restores the disruptor of telomeric silencing 1-like (DOT1L) function and could be an attractive therapeutic strategy for osteoarthritis." (PMID 38732122, 2024). "Local treatment with a selective hypoxia mimetic in the joint restores DOT1L function and could be an attractive therapeutic strategy for osteoarthritis." (PMID 34727094, 2021). "Importantly, we demonstrate that DOT1L contributed to the protective effects of hypoxia in articular cartilage and osteoarthritis." (PMID 34727094, 2021). "Modulating the DOT1L network might therefore be a therapeutic approach to protect the cartilage against osteoarthritis." (PMID 28627522, 2017).
osteoarthritis (continued). "Thus, we discovered that modulation of SIRT1 activity is a leading mechanism by which DOT1L controls activation of Wnt signalling, maintains cartilage health and prevents osteoarthritis." (PMID 28627522, 2017). "New epigenetics-based strategies, in particular those targeting the DOT1L network, could provide an innovative way for therapeutic modulation of Wnt signalling in joint disease and the development of effective treatments of osteoarthritis." (PMID 28627522, 2017). "DOT1L, which methylates lysine 79 of histone H3, is one of the targets of HIF-1α and contributes to the protective effects of hypoxia on osteoarthritis." (PMID 38732122, 2024). "Overall, our data demonstrate the importance of the DOT1L/SIRT1 axis in maintaining cartilage health and provides a rationale for potential therapeutic interventions in the treatment of osteoarthritis." (PMID 28627522, 2017). "The balance between DOT1L and SIRT1 activity determines the activation of Wnt signalling in cartilage, with excessive pathway activity resulting in osteoarthritis." (PMID 28627522, 2017). "Although increased ectopic bone formation around the knee joint was noted in 16‐month‐old Dot1l heterozygote mouse, this likely reflects osteophyte formation from accelerated osteoarthritis and is unlikely to affect survival." (PMID 32083237, 2020). "We did not detect differences in DOT1L gene expression levels between damaged or preserved cartilage from patients with osteoarthritis." (PMID 28627522, 2017). "In osteoarthritis, articular chondrocytes are not a uniform population and their health status may determine the expression of DOT1L at the individual cell level." (PMID 28627522, 2017). "To study whether cartilage degeneration in osteoarthritis is related to changes in DOT1L activity, we performed immunohistochemistry of DOT1L-methylated H3K79 on cartilage from non-osteoarthritic trauma patients and on preserved and damaged regions of cartilage from patients with osteoarthritis." (PMID 28627522, 2017).
breast tumor (4 papers, 2015 to 2022). "Moreover, DOT1L expression was found to be particularly elevated in estrogen receptor α (ERα)-positive breast tumors, where this associated with a worse clinical outcome." (PMID 35495127, 2022). "Together, these results indicate that DOT1L plays animportant role in breast tumour initiation by enhancing the self-renewal andtumorigenic ability of CSCs." (PMID 26199140, 2015). "Therefore, our data suggest that DOT1L-c-Myc-p300complex-mediated epigenetic control of EMT-TFs is important for regulation of theEMT and EMT-associated CSCs in breast tumour initiation and progression." (PMID 26199140, 2015). "Moreover, as anenhancer of EMT and CSC, DOT1L contributed to breast tumour initiation andEMT-mediated invasion and metastasis." (PMID 26199140, 2015).
ovarian tumors (4 papers, 2017 to 2024). "Together with evidence from loss-of-function genetic screens showing that ERα and DOT1L behave as core fitness factors in OC cells, these results suggest that combined inhibition of their activity might be effective against ERα-expressing, chemotherapy-resistant ovarian tumors." (PMID 31689915, 2019). "Taken together, these results indicate that DOT1L inhibition can be effective against a sizeable fraction of ovarian tumors." (PMID 31689915, 2019). "The effects of DOT1L on tumor growth in vivo were evaluated using an orthotopic ovarian tumor model." (PMID 28114995, 2017). "Furthermore, these results provide evidence suggesting that combined inhibition of these 2 factors (ERα/DOT1L) may be effective in blocking estrogen signaling in chemoresistant ovarian tumors." (PMID 38768082, 2024). "The expression of DOT1L and H3K79 methylation in 250 ovarian tumor samples and 24 normal ovarian samples was assessed by immunohistochemistry." (PMID 28114995, 2017). "Furthermore, patients with ovarian tumors with high DOT1L expression had shorter progression-free survival (PFS) and (OS) than patients with ovarian tumors with low DOT1L expression." (PMID 34253709, 2021). "DOT1L expression and H3K79 methylation was significantly increased in malignant ovarian tumors." (PMID 28114995, 2017).
colon adenocarcinoma (3 papers, 2019 to 2021). "Interestingly, DOT1L(K358) acetylation levels in primary colon adenocarcinomas with metastasis were significantly higher than in those without metastasis." (PMID 32042335, 2020).
head and neck cancer (3 papers, 2017 to 2025). A primary or metastatic malignant neoplasm affecting the head and neck. "Specifically, HA promotes DOT1L-regulated H3K79 methylation of miR-10b promoter binding sites leading to miR-10 production resulting in CSC-specific functions in head and neck cancer." (PMID 31293964, 2019). "Recent studies indicate that the activity of histone methyltransferase (e.g., DOT1L) can be detected in HA-activated head and neck cancer stem cells (CSCs)." (PMID 31293964, 2019). "Taken together, these recently discovered matrix hyaluronan (HA)/CD44v3-mediated signaling pathways and DOT1L-specific epigenetic regulation in head and neck CSCs could provide unique molecular targets and specific therapeutic drugs for the treatment of head and neck cancer." (PMID 28837080, 2017). "Studies on head and neck cancer have shown that hyaluronic acid (HA), a key component of the ECM, induces DOT1L activation, which consequently promotes tumor cell stemness." (PMID 41533929, 2025). "DOT1L-activated H3K79 methylation appears to be directly involved in the binding of the E-box elements at the miR-10b promoter leading to miR-10b gene expression and production in head and neck cancer CSCs treated with HA." (PMID 28837080, 2017).
head and neck squamous cell carcinoma (3 papers, 2018 to 2022). A squamous cell carcinoma that arises from any of the following anatomic sites: lip and oral cavity, nasal cavity, paranasal sinuses, pharynx, larynx, and salivary glands. "Furthermore, HA binding to CD44v3+ALDH+ CIC in head and neck squamous cell carcinoma (HNSCC) affects the activity of the histone methyltransferase DOT1L in regulating histone modifications and miRNA activation." (PMID 30211160, 2018). "DOT1L promotes miRNA-10b-mediated invasion and chemoresistance in head and neck squamous cell carcinoma (HNSCC) cancer stem cells." (PMID 31888761, 2019). "In head and neck squamous cell carcinoma (HNSCC), DOT1L involvement in regulation of cancer stem cell properties was recently demonstrated." (PMID 35495127, 2022).
influenza (3 papers, 2018 to 2020). An acute viral infection of the respiratory tract, occurring in isolated cases, in epidemics, or in pandemics; it is caused by serologically different strains of viruses (influenzaviruses) designated A, B, and C, has a 3-day incubation period, and usually lasts for 3 to 10 days. "Infection with either influenza or Sendai viruses stimulated luciferase accumulation in comparison with non-infected cells and pinometostat treatment caused a significant decrease of luciferase accumulation in the infected cells, reinforcing the role of DOT1L in controlling interferon signaling." (PMID 31727944, 2019). "The inhibition of Dot1l by pinometostat (EPZ) treatment or by Dot1L silencing, stimulated influenza and vesicular stomatitis virus replication." (PMID 32188146, 2020). "The role of Dot1L against infections was highlighted by an increase of influenza A and vesicular stomatitis virus replication in Dot1L-inhibited cells mediated by a decreased antiviral response." (PMID 32188146, 2020). "We previously reported that down-regulation of DOT1L increases influenza and vesicular stomatitis virus replication and decreases the antiviral response." (PMID 31727944, 2019). "Down-regulation of DOT1L stimulates influenza and vesicular stomatitis virus replication in cultured cells." (PMID 31727944, 2019).
osteoporosis (3 papers, 2018 to 2025). A condition of reduced bone mass, with decreased cortical thickness and a decrease in the number and size of the trabeculae of cancellous bone (but normal chemical composition), resulting in increased fracture incidence. "The trabecular bone loss was consistent with a recent study of DOT1L‐inhibitor treatment of ovariectomized mice, and increasing DOT1L activity may be therapeutic in human osteoporosis, particularly in postmenopausal women." (PMID 32083237, 2020). "In addition, the role of Dot1l in inhibiting osteoclast activity and preventing osteoporosis has been reported, but its regulatory role in osteogenesis remains unclear." (PMID 40677859, 2025). "In addition, DOT1L inhibition increased osteoclast surface area and accelerated bone-mass reduction in a mouse ovariectomy (OVX) model of osteoporosis without alter osteoblast differentiation." (PMID 29348610, 2018).
pancreatic cancer (3 papers, 2019 to 2023). "The potential of DOT1L as a therapeutic target was also demonstrated for a subset of pancreatic adenocarcinomas, where high levels of the enzyme were found in 4.4% of 230 pancreatic tumors analyzed." (PMID 35495127, 2022). "Histone methyltransferase Dot1L might inhibit pancreatic cancer cell apoptosis by targeting NUPR1, and overexpressed NUPR1 also inhibited pancreatic cancer cell apoptosis." (PMID 37626099, 2023).
rectal cancer (3 papers, 2019 to 2025). A primary or metastatic malignant neoplasm that affects the rectum. "Our previous work identified the DOT1L gene as a differentially methylated gene in rectal cancer patients whose methylation levels in pre-therapeutic rectal cancer biopsies was associated with a better outcome." (PMID 30616689, 2019). "We previously identified the DOT1L gene as 1 of 11 genes whose increased methylation is associated with better disease outcome in rectal cancer patients." (PMID 30616689, 2019). "In disagreement with these observations, an oncosuppressive role of DOT1L was observed instead in the rectal cancer cell line SW837." (PMID 35495127, 2022). "In addition, the same authors reported a significant correlation between high levels of DOT1L and H3K79me3 and increased OS in a cohort of 156 rectal cancer patients." (PMID 35495127, 2022). "In this study, we built upon these findings and examined whether rectal cancer patients may potentially be classified based on H3K79me3 levels or DOT1L mRNA levels." (PMID 30616689, 2019). "Similar results were observed in the rectal cancer cell line SW837, where the depletion of DOT1L also led to decreased induction of γH2AX 15 min after DSB induction, while pKAP1 levels were elevated compared to control cells." (PMID 30616689, 2019).
Ataxia (2 papers, 2019 to 2023). Ataxia refers to impaired coordination of voluntary muscle movement. "Disruptor of telomeric silencing 1-like (encoded by Dot1l) methylates histone H3, and conditional knockout of Dot1l in granule cell precursors causes cerebellar hypoplasia and ataxia." (PMID 36995257, 2023). "Dysregulation of expression of these candidates and/or processes might be implicated in the ataxia phenotype of Dot1l-cKOAtoh1." (PMID 30302725, 2019). "Despite the low numbers of direct targets genes revealed in this study, the identified targets might be relevant for proper cerebellar function and implicated in the mild ataxia phenotype of Dot1l-cKOAtoh1." (PMID 30302725, 2019). "Dysregulated expression of these target genes might be implicated in the ataxia phenotype observed in Dot1l-cKOAtoh1." (PMID 30302725, 2019). "In summary, this study reports on DOT1L target genes in the cerebellum that might account for the ataxia phenotype in mice with DOT1L-deficient granular cells in the cerebellum." (PMID 30302725, 2019). "Behavioral tests of mice with granule cell-specific DOT1L deletion in the cerebellum indicated a mild ataxia phenotype." (PMID 30302725, 2019). "In summary, our data showed that DOT1L function is needed for proper development and function of the cerebellum and that impaired DOT1L function results in ataxia in vivo." (PMID 30302725, 2019). "It is therefore likely that the increased level of Pcdh17 transcription in Dot1l-cKOAtoh1 resulted in synaptic impairment involved in the ataxia observed in these mice." (PMID 30302725, 2019). "DOT1L deficiency in granule cells, but not in PCs, led to an ataxia phenotype and a smaller sized cerebellum in mice." (PMID 30302725, 2019). "We identified a small number of candidate genes regulated by DOT1L in vivo and in vitro, misexpression of which might result in ataxia." (PMID 30302725, 2019).
atherosclerosis (2 papers, 2022). A disease characterized by the build-up of fatty material and calcium deposition in the arterial wall resulting in partial or complete occlusion of the arterial lumen. "It’s also demonstrated that Dot1L was involved in atherosclerosis development through NF-κB pathway." (PMID 35986422, 2022).
cervical cancer (2 papers, 2019 to 2022). A primary or metastatic malignant neoplasm involving the cervix. "DOT1L involvement in cervical cancers associated with persistent high-risk human papilloma virus (HR-HPV) infection has been recently demonstrated." (PMID 35495127, 2022). "Furthermore, DOT1L activity was reported as a crucial risk factor for the development of cervical cancer associated with the human papilloma virus (HPV) infection." (PMID 35495127, 2022).
diabetes (2 papers, 2016 to 2019). "It has been reported that increasing DOT1L expression by spironolactone or by stable transfection led to impaired endothelin-1 expression in NRK-52 cells, indicating a possible role of DOT1L in mediating the pathogenesis of diabetes." (PMID 31866860, 2019).
diabetic nephropathy (2 papers, 2016). "Moreover, depletion of DOT1L led to endogenous AQP5 upregulation, but the upregulated AQP5 contribute to polyuria in patients with diabetic nephropathy, suggesting that DOT1L is critical in renal water homeostasis with DN." (PMID 27846294, 2016).
fibrosis (2 papers, 2022). the formation of excess fibrous connective tissue in an organ or tissue in a reparative or reactive process. "Next, we generated mice with a whole-body knocking down to determine Dot1L functions in cardiac fibrosis." (PMID 35986422, 2022). "It is interesting to note that H3K79me3 occupancy on the promoter of Jag1 was markedly upregulated in TGF-β1-induced fibrosis, which was alleviated upon DOT1L inhibition with EPZ5676." (PMID 35039472, 2022). "Using combinative in vitro and in vivo studies, we demonstrated that Dot1L is a critical component of pro-fibrotic signaling in the heart, and determined the therapeutic potential of specific inhibitor EPZ5676 in cardiac fibrosis of post-MI." (PMID 35986422, 2022).
glioblastoma (2 papers, 2020 to 2022). The most malignant astrocytic tumor (WHO grade IV). "High levels of DOT1L were also detected in glioblastoma stem cells." (PMID 35495127, 2022).
hepatocellular carcinoma (2 papers, 2023 to 2025). A malignant tumor that arises from hepatocytes. "A recent study reported that SPDEF could bind to the miR-448 promoter to downregulate DOT1L, whereby promoting self-renewal of hepatocellular carcinoma stem cells." (PMID 37633945, 2023).
lung adenocarcinoma (2 papers, 2017 to 2026). A carcinoma that arises from the lung and is characterized by the presence of malignant glandular epithelial cells. "The H3K79 methyltransferase DOT1L mutations are less frequent and are described in 3% of lung adenocarcinomas." (PMID 28804523, 2017). "In lung adenocarcinomas, DOT1L has been recently described to be mutated in 3% of tumors, suggesting abnormal H3K79me in a subset of samples." (PMID 28804523, 2017). "Here, we demonstrate that DOT1L orchestrates immune evasion in lung adenocarcinoma (LUAD) through epigenetic activation of multiple immune checkpoints." (PMID 41836439, 2026).